PIGZ (phosphatidylinositol glycan anchor biosynthesis class Z (Gwada blood group))
Description:
Alpha-1,2-mannosyltransferase that catalyzes the transfer of the fourth mannose, via an alpha-1,2 bond, from a dolichol-phosphate-mannose (Dol-P-Man) to a 2-acyl-6-[alpha-D-mannosyl-(1->2)-alpha-D-mannosyl-(1->6)-2-phosphoethanolamine-alpha-D-mannosyl-(1->4)-alpha-D-glucosaminyl]-1-(1-radyl,2-acyl-sn-glycero-3-phospho)-1D-myo-inositol (also termed H6) intermediate to generate a 2-acyl-6-[alpha-D-mannosyl- (1->2)-alpha-D-mannosyl-(1->2)-alpha-D-mannosyl-(1->6)-2-phosphoethanolamine-alpha-D-mannosyl-(1->4)-alpha-D-glucosaminyl]-1-(1-radyl,2-acyl-sn-glycero-3-phospho)-1D-myo-inositol (also termed M4C) and participates in the twelfth step of the glycosylphosphatidylinositol-anchor biosynthesis (Probable). The presence of a fourth mannose in GPI is facultative, suggesting that it only exists in some tissues (Probable).
Synonyms: GPI-MT-IV; PIG-Z; hSMP3; SMP3; FLJ12768; MGC52163
Tractability: Antibody: UniProt predicts a signal peptide or a membrane-spanning region.
Gene: Protein-coding gene on chromosome 3 (196,946,356 to 196,969,060, reverse strand). Ensembl gene ENSG00000119227.
Subcellular location: Endoplasmic reticulum membrane
Pathways (Reactome):
Metabolism of proteins: Synthesis of glycosylphosphatidylinositol (GPI)
Gene Ontology:
Molecular function: dol-P-Man:Man(3)GlcN-acyl-PI alpha-1,2-mannosyltransferase activity; mannosyltransferase activity; alpha-1,2-mannosyltransferase activity; glycosyltransferase activity
Biological process: GPI anchor biosynthetic process
Cellular component: endoplasmic reticulum; endoplasmic reticulum membrane
Genetic constraint (gnomAD): Loss-of-function variants: 19 observed, 19.47 expected, observed/expected ratio (o/e) 0.98, 90% interval 0.68 to 1.43. The upper end of that interval is the gene's LOEUF score, 1.43, which puts it in group 5 of 6, group 1 being the genes least tolerant of losing a copy. Missense variants: 748 observed, 727.28 expected, observed/expected ratio (o/e) 1.03, 90% interval 0.97 to 1.09. Synonymous variants: 396 observed, 332.96 expected, observed/expected ratio (o/e) 1.19, 90% interval 1.1 to 1.29.
Homologues: Orthologues: chimpanzee PIGZ (98% identical), macaque PIGZ (94% identical), rabbit PIGZ (80% identical), guinea pig Pigz (77% identical), tropical clawed frog PIGZ (35% identical).
Diseases named in the same sentence as PIGZ in open-access papers:
PIGZ is named in the same sentence as 10 diseases in open-access papers, as found by Europe PMC text mining. Sharing a sentence is not in itself a finding about the gene and the disease. The quoted sentences say what the papers report.
myelogenous leukemia (1 paper, 2023). "The second DMR is distant from the transcriptional initiation site of the PIGZ gene but partially overlaps with a Histone H3 lysine 27 acetylation (H3K27ac) mark (associated with active enhancer function) in the human immortalized myelogenous leukemia cell line K562." (PMID 37662940, 2023).
neuroblastoma (1 paper, 2025). Neuroblastoma (NB) is the most common solid, extracranial childhood tumor. "We also observed the deregulation of PIGA and PIGZ in MYCN-A neuroblastoma." (PMID 39860532, 2025).
Obesity (1 paper, 2019). Accumulation of substantial excess body fat. "In all three discovery analyses, in addition to loci mapping to established BMI and obesity loci, we identified PIGZ and C3orf38, two putative novel loci in the thin vs control analysis, that reached conventional genome-wide significance (GWS) (p≤5x10-8)." (PMID 30677029, 2019).
tumor (3 papers, 2022 to 2026). "Some glycosylation factors showed genomic alterations (SNVs and CNVs) in 15% of tumor samples (namely GPAA1, PIGZ and B3GNT5) with a predominance of amplifications." (PMID 36009354, 2022). "The dysregulation of PIGA and PIGZ may alter the function and expression of GPI-anchored proteins, potentially contributing to tumor progression and immune evasion mechanisms." (PMID 39860532, 2025).
cancer (1 paper, 2022). A tumor composed of atypical neoplastic, often pleomorphic cells that invade other tissues. "GPAA1, PIGZ and PIGX amplifications are associated with worse prognosis at a pan-cancer level." (PMID 36009354, 2022).
PIGZ also shares sentences with these, for which no sentence is quoted: colorectal cancer (1 paper); gout (1); hyperuricemia (1); leishmaniasis (1); visceral leishmaniasis (1).